DAPK1 (death associated protein kinase 1)
Diseases named in the same sentence as DAPK1 in open-access papers (continued):
Sharing a sentence is not in itself a finding about the gene and the disease.
colorectal cancer (29 papers, 2002 to 2025). A primary or metastatic malignant neoplasm that affects the colon or rectum. "One study showed loss of DAPK1 in colorectal cancer cells enhanced tumor budding in vivo in the chorioallantoic membrane (CAM) model." (PMID 34831219, 2021). "In human colorectal cancer tissues, the co-expression of DAPK1 and p38 was associated with apoptotic cell death." (PMID 30287790, 2018). "Several studies provided direct evidence for the interaction of DAPK1 with p38 signaling in inflammation-associated colorectal cancer cells." (PMID 30287790, 2018). "Analysis of normal human tissue and primary colorectal cancers showed the expression of the s-DAPK-1 mRNA, indicating that it is expressed in vivo." (PMID 37372454, 2023). "In light of previous scientific inquiries, it’s compelling to mention that many of the genes within this list of 10, specifically CAV1, DAPK1, GPX3, IGFBP6, TIMP1, GADD45B and ENO2 have been found associated intimately with colorectal cancer, as documented by several research studies." (PMID 38501104, 2024). "The DNA methylation patterns in the CpG island of the O6-methylguanine-DNA methyltransferase (MGMT), p16, deleted in colorectal cancer (DCC) and death-associated protein kinase 1 (DAPK1) genes were determined by sodium bisulfite treatment and subsequent methylation-specific PCR MS PCR." (PMID 19830138, 2009). "Similarly, our results showed the mRNA of DAPK1 was increased in HT-29 (a type of early-stage colorectal cancer cell) and reduced in advanced-stage cell lines, such as HCT116, SW480, and SW620, indicating that the downregulation of DAPK1 has a connection with COAD progression." (PMID 40236629, 2025). "Among these three miRNAs, we found miR-26a-5p was reported to regulate autophagy in colorectal cancer, osteosarcoma, hepatocellular carcinoma, glioma, and laryngeal squamous cell carcinoma by targeting ULK1/2, DAPK1, and ATG12." (PMID 34740994, 2021). "Finally, the six selected genes (SIRT3, PIK3CA, ITGA3, DAPK1, PAK1, and CASP3) have been reported in colorectal cancer." (PMID 38213716, 2024). "There is only one report on the expression of s-DAPK-1 in cancer, where the mRNA expression of s-DAPK-1 with that of DAPK-1 in HCT116 colorectal cancer cells, A375 skin cancer cells and non-cancerous kidney cells (Hek-293) were compared." (PMID 37372454, 2023). "The results of mRNA quantification in cancer cells indicated that, contrary to DAPK-1, s-DAPK-1 is not expressed in colorectal cancer cells, and its mRNA expression in skin cancer cells is significantly higher than that of DAPK-1." (PMID 37372454, 2023).
bladder cancer (23 papers, 2007 to 2025). "The bladder cancer data set showed that the expression of the ACOX1 gene was significantly associated with the expression of DAPK1." (PMID 41407823, 2025). "In the present study, we found that DAPK1 expression was negatively associated with tumor stage and a low level expression of DAPK1 in bladder cancer specimens were associated with shorter survival in bladder cancer patients in 3 independent bladder cancer datasets (n = 462)." (PMID 28388658, 2017). "Drug interaction mapping identified nine target genes (e.g., DAPK1, ATR, and MTR) associated with eight FDA-approved bladder cancer therapies, including cisplatin and gemcitabine." (PMID 40940866, 2025). "Compared to normal tissue, hypermethylation of DAPK1 has been routinely observed in many cancers, including lung, kidney and bladder cancers." (PMID 36290392, 2022). "This compound induces cancer cell apoptosis by demethylation of death-associated protein kinase 1 (DAPK-1) and Ras-association domain family 1α (RASSF-1α) genes via antioxidant activity in T24 and 5637 bladder cancer cells." (PMID 33996570, 2021). "In this patient cohort, DAPK1 expression was significantly lower in bladder cancer specimens with a T2 stage or above compared to those with Ta or T0 stage (p = 0.011)." (PMID 28388658, 2017). "Further in vitro study is required to establish the functional role of DAPK1 in FGFR3-activating bladder cancer." (PMID 28388658, 2017). "Previous results have shown that DAPK1 promoter was hypermethylated in the majority of bladder cancer specimens, however, the prognostic significance of DAPK1 in bladder cancer has yet to be demonstrated." (PMID 28388658, 2017). "Molecular signature was available in GSE32894 dataset, and we also found that DAPK1 expression was significantly lower in the more aggressive subtypes of bladder cancer, Urobasal B (MS2b2.1) and SCC-like (MS2b2.2) subtypes (p < 0.001)." (PMID 28388658, 2017). "DAPK1 expression was significantly higher in bladder cancer with a Ta or T1 stage compared to those with T2 stage or above (p = 0.012)." (PMID 28388658, 2017). "Demethylating agents have been shown to reverse the hypermethylation status of DAPK1 promoter leading to re-expression of DAPK1 mRNA resulting in retarded growth of bladder cancer cell lines." (PMID 28388658, 2017). "In the present study, we have found that TRAK1 was co-regulated with DAPK1 and was a favorable prognostic marker in bladder cancer." (PMID 28388658, 2017). "DAPK1 was knocked down in a bladder cancer cell lines, T24, and mRNA expression levels of these genes were measured." (PMID 28388658, 2017). "Our results show that TRAK1 expression was significantly associated with both DAPK1 expression and survival consistently in all the three bladder cancer patient cohorts and suggest that TRAK1 is a favourable prognostic marker in bladder cancer." (PMID 28388658, 2017). "In this patient cohort, DAPK1 expression was significantly lower in bladder cancer specimens with a T2 stage or above compared to those with Ta or T1 stage (p = 0.002)." (PMID 28388658, 2017). "Together, our results suggest that DAPK1 is an important prognostic marker and therapeutic target for bladder cancer and have identified possible therapeutic agents for future testing in bladder cancer models with low DAPK1 expression." (PMID 28388658, 2017). "Pathway analysis of affymetrix data file shows upregulation of four genes ERBB2, DAPK1, FGFR3 and CDKN2A which have reference to prove their involvement in causing bladder cancer." (PMID 22276047, 2011). "5-Aza restores the expression of DAPK1 in bladder carcinoma and B-cell lines and the re-expression of DAPK1 in Burkitt's lymphoma cell lines restores the susceptibility to IFN-α triggered apoptosis." (PMID 21108789, 2010). "Knockout of DAPK1 in the T24 cells of bladder cancer downregulated the expression of ACOX1." (PMID 41407823, 2025).
bladder cancer (continued). "We found that the expression levels of DAPK1 and TRAK1 were positively significantly correlated with each other and that a low level expression of TRAK1 was associated with a poorer survival in the three bladder cancer patient cohorts." (PMID 28388658, 2017). "Our results suggest that reduced expression of DAPK1 may lead to bladder cancer with a more aggressive phenotype." (PMID 28388658, 2017). "DAPK1 promoter methylation has been detected in majority of bladder cancer specimens, transcriptional dyeregulation could be one of the major steps for DAPK1 downregulation in bladder cancer." (PMID 28388658, 2017). "In conclusion, our data show that DAPK1 could be a suppressor in bladder cancer progression, and suggest that DAPK1 could be a potential biomarker and therapeutic target in bladder cancer." (PMID 28388658, 2017). "Our results suggest that inhibition of Braf may be a potential therapeutic approach for patients with bladder cancer, while this approach may be more effective in treating bladder cancer with a high level expression of DAPK1." (PMID 28388658, 2017). "Indeed, treatment of vemurafenib in T24 bladder cancer cells resulted in upregulation of DAPK1 confirming our connectivity mapping, while knockdown of DAPK1 resulted in reduced sensitivity towards inhibition of Braf signaling by vemurafenib." (PMID 28388658, 2017). "Knockdown of DAPK1 in bladder cancer T24 cells resulted in downregulation of ACOX1, UPK2 and TRAK1." (PMID 28388658, 2017). "DAPK1 promoter has been shown to be hypermethylated in bladder cancer." (PMID 28388658, 2017). "Our results suggest that in a background of low FGFR3 expression, its activating mutation may play a significant role in suppressing the expression of DAPK1 in bladder cancer." (PMID 28388658, 2017). "DAPK1 is an important prognostic marker and therapeutic target for bladder cancer, while vemurafenib and trimetinib may be potential targeting drugs for DAPK1 in bladder cancer." (PMID 37576398, 2023). "Importantly, we identified via connectivity mapping that inhibition of Braf/MEK/ERK pathway may be a potential therapeutic approach for bladder cancer with reduced expression of DAPK1." (PMID 28388658, 2017). "Hypermethylation of tumor suppressor genes, including DAPK-1 and RASSF-1α genes, have been found in patients with bladder carcinoma (BC) in some western countries." (PMID 28435431, 2017). "Collectively, dioscin induces demethylation of DAPK-1 and RASSF-1α genes via the antioxidant capacity, resulting in apoptosis of bladder cancer T24 cells or inhibitory cell viability." (PMID 28435431, 2017). "Further analysis of the 3 independent bladder cancer datasets have identified ACOX1, UPK2, TRAK1, PLEKHG6 and MT1X genes had their expression significantly correlated with that of DAPK1." (PMID 28388658, 2017). "Further investigation showed that FGFR3 knockdown resulted in downregulation of DAPK1 in bladder cancer cell line, suggesting that FGFR3 may be an upstream factor of DAPK1." (PMID 28388658, 2017). "In addition, we found that FGFR3 knockdown downregulated DAPK1 in bladder cancer cell line, and TREK1 is coregulated with DAPK1 and a low level expression of TREK1 was also correlated with poor survival in 3 independent bladder cancer patient cohorts." (PMID 28388658, 2017). "Using microarray data generated from bladder cancer cell line, RT112, with inducible knockdown of FGFR3 from three different shFGFR3 sequences, we found that DAPK1 expression was upregulated by knockdown of FGFR3 in inducible conditions for all the three different shFGFR3 sequences (p < 0.001)." (PMID 28388658, 2017). "In a study with 34 bladder cancer samples, the correlation between DAPK1 mRNA expression and tumor staging and grading could not be established." (PMID 28388658, 2017).
colon cancer (23 papers, 2009 to 2024). "The significant downregulation of DAPK1 in colon cancer is associated with miR103 and miR107, which are closely related to patient prognosis." (PMID 39057063, 2024). "Models of colon cancer have shown that the loss of DAPK1 expression has been shown to impact migratory capacity, tumour cell dissemination and increase invasiveness." (PMID 36008952, 2022). "We show that under DAPK1 loss, colon tumor cells gain ability to modulate the ECM consequently increasing their metastatic potential in vitro and in vivo." (PMID 31772156, 2019). "In fact, ISL was found to induce G2 cell cycle arrest, and to have an effect on death-associated protein kinase 1 (DAPK1) promoter methylation in the colon cancer cell line, indicating its role in influencing the epigenetic regulation of genes associated with cancer." (PMID 38140059, 2023). "In colon cancer, hypoxic conditions increased the expression of miR 103/107 while decreasing the expressions of both DAPK1 and KLF4, thereby promoting cancer metastasis." (PMID 39057063, 2024). "Otherwise, the protein expression levels of TRADD, H2AC6, VDAC3, JMJD7-PLA2G4B, TRAF2, and DAPK1 in colon cancer tissues and normal tissues in the HPA database were shown, which were consistent with the expression levels of these genes in RNA levels." (PMID 36505813, 2022). "In HCT-116 colon cancer cells, the combination of butyrate and DHA significantly reduced methylation of genes encoding the proapoptotic Bcl2l11, Cideb, Dapk1, Ltbr, and Tnfrsf2." (PMID 29259973, 2017). "According to our transcriptome data, DAPK1 (reported to be a tumor suppressor candidate) is down expressed in breast, colon cancer, leukemia, neuroblastoma and is methylated in all models analyzed." (PMID 19402918, 2009). "We obtained the risk score of each case with colon cancer; risk score = (0.46121 × expression of ULK3) + (0.650715 × expression of ATG101) + (1.521474 × expression of MAP1LC3C) + (0.641122 × expression of TSC1) + (0.243022 × expression of DAPK1) + (-0.17015 × expression of SERPINA1)." (PMID 34315829, 2021). "To confirm the successful induction of the 6 model genes (SIRT3, PIK3CA, ITGA3, DAPK1, PAK1, and CASP3), we gathered a set of 39 colon cancer tissue samples." (PMID 38213716, 2024). "Besides, the staining level of DAPK1 and ULK3 were reduced in colon cancer." (PMID 34315829, 2021). "We identified 6 prognostic-related ARGs (ULK3, ATG101, MAP1LC3C, TSC1, DAPK1 and SERPINA1) to formulate a novel autophagy-related signature, which could stably predict the survival of patients and indicate the extent of immunosuppressive microenvironment in colon cancer." (PMID 34315829, 2021).
Alzheimer disease (22 papers, 2009 to 2026). A progressive, neurodegenerative disease characterized by loss of function and death of nerve cells in several areas of the brain leading to loss of cognitive function such as memory and language. "For example, bioinformatics tools predicted death-associated protein kinase 1 (DAPK-1) as the most promising Alzheimer’s disease (AD)-related target for quercetin." (PMID 40699815, 2025). "DAPK1 is also associated with the accumulation of amyloid-β and tau proteins in the brain in Alzheimer’s disease (AD)." (PMID 33520249, 2021). "KLHL20 is a related CUL3-dependent ubiquitin ligase linked to autophagy, cancer, and Alzheimer's disease that promotes the ubiquitination and degradation of substrates including DAPK1, PML, and ULK1." (PMID 31279627, 2019). "While DAPK1 has been implicated in Alzheimer's disease through its role in tau aggregation and amyloid-β production, our findings suggest that DAPK1 may also influence PD-related pathways by phosphorylating parkin at Ser136 and Ser198." (PMID 41943176, 2026). "Since DAPK-1 is essential for the death and loss of neuronal cells under various stimuli, DAPK-1 inhibitors may offer a novel therapeutic strategy for neurological diseases such as ischemia and Alzheimer’s disease." (PMID 37372454, 2023). "Death-associated protein kinase 1 (DAPK1), as a calcium/calmodulin (CaM) regulated serine/threonine kinase, functions in apoptotic and autophagy pathways and represents an interesting drug target for inflammatory bowel disease and Alzheimer’s disease." (PMID 36291604, 2022). "DAPK1 is also associated with late-onset Alzheimer’s disease (LOAD)." (PMID 27445685, 2016). "Phosphorylation of NDRG2 at Ser350 is mediated by death-associated protein kinase 1 (DAPK1), which has been linked to neuronal cell death in multiple neurological diseases such as Alzheimer’s disease." (PMID 40378957, 2025). "For instance, in Alzheimer’s disease miR-143-3p inhibits amyloid precursor protein (APP) phosphorylation and beta-amyloid (Aβ) generation by targeting death-associated protein kinase 1 (DAPK1)." (PMID 39402582, 2024). "Abnormal upregulation of DAPK1 is observed in human patients with neurological diseases, such as Alzheimer’s disease (AD) and epilepsy." (PMID 37047515, 2023). "Death-associated protein kinase 1 (DAPK1), a Ca2+/calmodulin-dependent serine/threonine-protein kinase, promotes neurons apoptosis in ischemic stroke and Alzheimer’s disease (AD)." (PMID 35783103, 2022). "DAPK1 is considered to be a promising molecular target for the treatment of Alzheimer’s disease (AD)." (PMID 33520249, 2021). "Recently, DAPK1 was found to contribute to cortical spine and synapse degeneration after ischemia in vivo, and genetic deletion of the DAPK1 catalytic domain reversed hippocampal spine and synapse loss in Tg2576-APP Alzheimer disease mice." (PMID 33250715, 2020). "Elevated DAPK1 expression has been observed in Alzheimer’s disease (AD), where it may contribute to pathogenesis by modulating apoptosis, inflammatory responses, and pathways associated with neuronal synaptic damage." (PMID 39926603, 2024). "A large number of studies have proven that DAPK1 plays an Important role in mediating the pathological process of acute and chronic neurological disorders, such as Alzheimer’s disease (AD), Parkinson’s disease (PD), Huntington’s disease (HD), traumatic brain injury (TBI), stroke, and epilepsy." (PMID 37047515, 2023). "DAPK-1 deregulation also contributes to neurological disorders including ischemic stroke and Alzheimer’s disease by directly phosphorylating Tau on Ser262, resulting in cortical neuron spine damage and also through its involvement in the neurotoxicity of amyloid-β (Aβ)." (PMID 37372454, 2023). "In an Alzheimer’s disease (AD) model, DAPK-1 mediated neuronal cell death." (PMID 37372454, 2023).
Alzheimer disease (continued). "Death-associated protein kinase 1 (DAPK1) is a Ca2+/calmodulin-dependent serine/threonine-protein kinase, which promotes neuronal apoptosis in neurons during various neurological disorders such as ischemic stroke and Alzheimer’s disease (AD)." (PMID 35783103, 2022). "In addition, elevated DAPK1 activity is detected following brain injury due to ischemia, seizure, epilepsy, and Alzheimer’s disease (AD) as well as in response to ceramide and glutamate toxicity, indicating a close relationship between DAPK1 and neuronal cell death." (PMID 30287790, 2018).
non-small cell lung carcinoma (21 papers, 2006 to 2025). A group of at least three distinct histological types of lung cancer, including non-small cell squamous cell carcinoma, adenocarcinoma, and large cell carcinoma. "DAPK1 has been implicated in non-small cell lung cancer (NSCLC), where its overexpression under conditions of oxygen and glucose deprivation induces excessive autophagy and apoptosis in A549 cells." (PMID 40088196, 2025). "Death-associated protein kinase (DAPK1) promoter methylation has been shown to correlate with clinicopathological and prognostic features in non-small cell lung cancer patients." (PMID 32647312, 2020). "DAPK1 promoter hypermethylation correlates with reduced sensitivity to radiochemotherapy in stage I non-small-cell lung cancer patients." (PMID 33201837, 2020). "CpG methylation in the DAPK1 promoter region has been detected in a range of solid cancers, such as non-small cell lung cancer, leiomyosarcoma, nasopharyngeal carcinoma, and hematological malignancies, such as follicular lymphoma and CML." (PMID 25435999, 2015). "However, DAPK1 expression is frequently downregulated in B cell lymphoma and non-small cell lung cancer through multiple mechanisms, including promoter methylation." (PMID 31336860, 2019). "All of those changes of non-small cell lung cancer metastasis and occurred early in neoplastic evolution may be induced by DAPK1 and other tumor supressor genes." (PMID 21264081, 2008). "The imbalance between pro- and anti-apoptotic factors may lead to accumulation of transforming mutations and resistance or decreased sensitivity to anticancer treatment, as shown for APAF-1 inactivation in human leukaemic cells or DAPK-1 inactivation in non-small cell lung cancer cells." (PMID 17133271, 2006).